MAP2 (microtubule associated protein 2)
Diseases named in the same sentence as MAP2 in open-access papers (continued):
Sharing a sentence is not in itself a finding about the gene and the disease.
tauopathy (12 papers, 2014 to 2026). Neurodegenerative disorders involving deposition of abnormal tau protein isoforms (tau proteins) in neurons and glial cells in the brain. "Dysregulation of MAP2 is associated with tauopathies, given that MAP2 shares sequences homology with tau and can inhibit its aggregation by binding to the ends of the tau fibrils." (PMID 38726308, 2024). "To explore the effect of APOE4 on neuronal loss and tauopathy, we determined the number of NeuN+ cells and intensity of NeuN, MAP2, phospho-tau (p-S202/T205) (AT8) and phospho-tau (p-T231) (AT180) via immunostaining." (PMID 39468688, 2024). "The abnormally hyperphosphorylated tau sequesters the microtubule associated proteins (MAP-1 and MAP-2) or normal tau, resulting in the breakdown of the microtubule networks, and subsequent neurofibrillary degeneration and other tauopathies may develop." (PMID 25903151, 2015). "Finally, a new hypothesis regarding the roles of microtubule-associated protein 2 (MAP2) and tau in the pathogenesis of tauopathy is discussed." (PMID 28082867, 2016). "In brains affected by tauopathy, the somatodendrites containing MAP2 overlap with the area where tau pathology is observed." (PMID 28082867, 2016). "Does microtubule-associated protein 2 (MAP2), which shares carboxyl-terminal sequences with tau, also induce neurotoxicity and associate with tauopathies?" (PMID 28082867, 2016). "The present study raises the possibility of a pathoetiological role of MAP2 in the generation of AD and tauopathies." (PMID 24587039, 2014). "Because acquisition of Sarkosyl insolubility is a significant characteristic of deposited Tau in tauopathies, we first examined the Sarkosyl insolubility of MAP2 in the brains of AD patients and normal controls." (PMID 24587039, 2014). "MAP2 and Tau share highly homologous carboxyl-terminal sequences, but current information about the relationship between MAP2 and tauopathies is far from convincing." (PMID 24587039, 2014). "MAP2 has generally not been considered as a potential pathogenic agent in the tauopathies, as its presence in NFTs has been a subject of some debate and it forms no analogous aggregates." (PMID 36187353, 2022). "In this revised framework, interactions between MAP2 and soluble Tau may be important in shaping tauopathy." (PMID 36187353, 2022). "Thus, understanding the properties of MAP2 will help us better understand the pathogenesis of tauopathy." (PMID 28082867, 2016). "MAP2 may also be involved in the pathogenesis of tauopathies, but it is difficult to find MAP2 inclusions because of its weak fiber-formation abilities." (PMID 28082867, 2016). "Thus, one should not exclude the potential pathological role of MAP2 in the pathogenesis of AD and tauopathies simply because MAP2 barely accumulates in NFTs or in neurons." (PMID 24587039, 2014). "Thus, MAP2 remains an active element to consider in the pathogenesis of tauopathies." (PMID 36187353, 2022). "We first detected morphological changes in the primary tauopathy neurons after SGC707 treatment; MAP2 signals were used to outline neuronal morphology." (PMID 40344412, 2025). "In a AAV-hTau-P301L tauopathy model, CP1 treatment suppressed tau hyperphosphorylation, preserved NeuN- and MAP2-positive neurons, attenuated astrocytic and microglial activation, and ultimately restored learning and memory abilities in both male and female mice." (PMID 42157943, 2026). "Co-staining of the dendritic marker MAP2 with Cav-1 showed decreased MAP2 expression in the hippocampal CA1 subfield and cortex in PSAPP-SynRFP, similar to that observed in postmortem human brains of patients diagnosed with CTE, tauopathy, and AD." (PMID 33981778, 2021).
Anxiety (10 papers, 2015 to 2024). Intense feelings of nervousness, tension, or panic often arise in response to interpersonal stresses. "In APOE knockout mice expressing human APOE4, enhanced measures of anxiety are associated with reduced microtubule-associated protein 2 (MAP2)-positive neuronal dendrites in the central nucleus of the amygdala." (PMID 39703925, 2024). "In rodents, it has been shown that loss of MAP-2 expression is associated with neuronal degeneration, which has short- and long-term effects on cognition and anxiety-related behavior." (PMID 31191328, 2019). "Specificity protein 2 (Sp2, rs3708840), tryptophan hydroxylase 1 (Tph1, rs262731280) and serotonin receptor 3A (Htr3a, rs50670893) were associated with activity/anxiety behaviours, and microtubule-associated protein 2 (Map2, rs13475902) was associated with cognitive performance." (PMID 28145470, 2017). "This indicated that animals with lower levels of GFAP and MAP2 exhibited greater anxiety-like behaviors." (PMID 34955781, 2021). "Recent evidence suggests hyperphosphorylation of neurofilaments and decreased MAP-2 levels in the hippocampus are correlated with cognitive and anxiety dysfunctions in murine models of neurodegeneration and global cerebral ischemia, respectively." (PMID 29662433, 2018). "Potential correlations between MAP2 and GFAP positive signal (area fraction) and anxiety-like behaviors (time spent in the enclosed, safe arm of the EPM) were investigated." (PMID 34955781, 2021).
glioblastoma (10 papers, 2009 to 2025). The most malignant astrocytic tumor (WHO grade IV). "The high positive rates of TUJ1 and MAP2 in GFP+ cells of the GFP+NeuroD4 group lead us to conclude that NeuroD4 overexpression efficiently reprograms specific glioblastoma cell types into neuron-like cells." (PMID 37582760, 2023). "The high TUJ1 and MAP2 positivity rates in M-cherry+ cells led us to conclude that knocking down PTBP1 alone can efficiently convert specific types of glioblastoma cells into a neural differentiation state." (PMID 35664063, 2022). "In these samples, MAP2 marks neurons, synapsin-1 marks presynaptic puncta, Homer-1 marks postsynaptic puncta, and SB28 glioblastoma cells are inherently labeled by GFP." (PMID 40404658, 2025). "Glioblastoma cells forming aggregates, as well as undifferentiated GFAP+NNP, co-expressed SOX-2, Nestin, Beta III-tubulin, MAP2, GFAP, Vimentin, Fibronectin and CD44, when cultured under serum-starvation media." (PMID 19216795, 2009). "Considering our data, and recent literature demonstrating mesenchymal differentiation of glioblastoma cells, we defined the CD44+, GFAP-, MAP2- population of glioblastoma cells as mesenchymal." (PMID 19216795, 2009). "We first confirmed our previous findings that NGN2, as a pioneer factor, could reprogram U251 human glioblastoma cells into neurons that are marked by expression of TUJ1 and MAP2." (PMID 39390804, 2024). "Further in silico analysis of TIMER2 glioblastoma patient data sets also suggested that RCN3 showed a positive correlation with stemness marker CD44 and a negative correlation with differentiation markers such as ID4, MAP2, and NTRK5." (PMID 37046668, 2023). "The results showed that NGN2 and SOX4/11 could reprogram primary glioblastoma cell lines (GBM) into neuron‐like cells with approximately 95% efficiency, as measured by the ratio of cells expressing TUJ1 and MAP2." (PMID 39390804, 2024). "Glioblastoma stem cell cultures, shifted for 15 days in serum-containing medium, undergo astrocytic and/or neural differentiation (i.e., increased expression of GFAP and MAP-2) representing an in vitro model of the bulk of heterogeneous non-stem cells in GBM mass." (PMID 30186163, 2018). "The traditional glioblastoma prognostic markers GFAP, S100, OLIG2, MAP2 and SYN were also analyzed and found to be indistinguishable among the intracranial glioblastoma xenografts." (PMID 25955030, 2015). "In our culture model, a population of glioblastoma cells was able to form aggregates composed of cells with multilineage phenotype, i.e. showing expression of: CD44, Vimentin, GFAP, Nestin, Beta III-tubulin, MAP2, Fibronectin and SOX-2, but not CD133." (PMID 19216795, 2009).
Parkinson disease (9 papers, 2016 to 2025). A progressive degenerative disorder of the central nervous system characterized by loss of dopamine producing neurons in the substantia nigra and the presence of Lewy bodies in the substantia nigra and locus coeruleus. "Irregular Cdk5 activation and its phosphorylation of substrates as tau, MAP2, and MAP1b have been associated with pathological conditions, such as Alzheimer and Parkinson’s diseases." (PMID 35182267, 2023). "Acteoside significantly attenuated Parkinsonism symptoms by inhibiting rotenone-induced α-synuclein and caspase-3 upregulation, and microtubule-associated protein 2 downregulation in PD rats." (PMID 29344414, 2017). "We conducted an analysis using a confocal microscope to examine the expression of three neuronal markers that are generally downregulated in Parkinson’s disease patients, glial fibrillary acidic protein (GFAP), tyrosine hydroxylase (TH), and microtubule-associated protein 2 (MAP2)." (PMID 40227236, 2025). "In this regard, the markers NeuN and MAP-2 were used to measure cytotoxicity and also to confirm their maturity and neuronal nature; these markers are employed in the study of different neurodegenerative diseases, such as Parkinson’s or Alzheimer’s." (PMID 35324672, 2022). "PEA protected from the decrease in MAP-2 expression induced by amyloid peptides and by MPTP in an animal model of Parkinson’s disease." (PMID 31969800, 2019). "Notably, dystonia or Parkinson-related proteins are altered in the XDP MSNs proteome, including ATP1A3, COL6A3, GBA, GIGF2, HTRA2, MAP2, SNCA, and TORAIP2." (PMID 38042508, 2024).
cognitive decline (7 papers, 2020 to 2026). "Seven of the 22 peptides associated with the frail vs control diagnostic contrast and cognitive decline were cytoskeleton-related, including proteoforms of MAP2, VIM, TUBB, DBN1, TUBA8, PALM and NEFM." (PMID 38531951, 2024). "Furthermore, inflammatory mediators compromise the integrity of microtubule-associated protein 2 (MAP2), disrupting neuronal structure and function, which culminates in dendritic damage and cognitive decline." (PMID 41470904, 2025). "We observed a significant decreased expression of MAP-2 (p = 0.016377), SNAP25 (p = 0.0128) and CAMK2 (p = 0.003930) suggesting that inhibition of Nrgn expression induced by overexpression of the lncRNA caused disruption of synaptodendritic integrity, which is implicated in cognitive decline." (PMID 38659061, 2024). "Interestingly, MAP2 protein expression was increased 12 days post 20 Gy in multiple regions of the brain, which could be related to cognitive decline since the upregulation of Map2 expression has been shown to be correlated with cognitive decline in aging rodents." (PMID 38891920, 2024).
breast carcinoma (6 papers, 2012 to 2025). "Moreover, MAP2 expression in breast cancer specimens was correlated with increased sensitivity for paclitaxel." (PMID 38310601, 2024). "Elevation of MAP2 in breast cancer cell lines leads to increased paclitaxel sensitivity, and gene expression analysis revealed that MAP2 had significantly higher levels of expression in patients achieving a pathologic complete response to neoadjuvant paclitaxel with radiation treatment." (PMID 37569629, 2023). "Tumour cell MMP3 expression was reported to be a prognostic factor for poor survival in breast cancer, and MAP2 expression was shown to be significantly associated with pathological responses to neoadjuvant chemotherapy, regardless of breast cancer subtype." (PMID 29675884, 2018). "Its role in breast cancer is largely unknown, but the gene’s regulation of Map2, NGF and TrkA suggests an involvement in cell proliferation and renewal." (PMID 26960204, 2016). "“Elevation of MAP2 in breast cancer cell lines led to increased paclitaxel sensitivity”." (PMID 23216862, 2012).
neuritis (6 papers, 2018 to 2024). A neuropathy arising from inflammation of one or more nerves. "In contrast, AAV-Re-Gata3-GFP infection induces weak Map2 expression and limited neurite growth in GFP-positive neurocytes, while the GFP-negative neurons show strong Map2 staining and distinct neuritis (White arrow)." (PMID 36430332, 2022). "With immunofluorescent staining for Map2 and NeuN, neuronal morphology could be identified and analyzed based on its neuritis characters." (PMID 34638996, 2021). "Phase-contrast microscopy results representedneuronal-like cells appeared after neural tube structuresplating on PLO/Laminin coated culture dishes (stage 4)and the cells neuritis wildly spread during next days.These cells expressed neural markers such as TUJ1and MAP2 in stage 4." (PMID 29105388, 2018). "Moreover, we confirmed the degeneration of DA neurons treated with CBE (long-term treatment) by immunofluorescence analyses against MAP2 and Tuj1, showing neuritis fragmentation and degeneration, and by the halving of the cell number compared to the untreated cells." (PMID 35954187, 2022).
astrocytomas (5 papers, 2014 to 2025). "Interestingly, we also found that some neuronal markers such as DCX, MAP2 and NeuN were highly expressed in astrocytomas." (PMID 31212628, 2019). "Few BNET variants can thereby present with a predominant glial cell population (astroglial or with clear cell morphology), which need to be distinguished from diffusely infiltrating astrocytomas or oligodendrogliomas using appropriate immunohistochemical markers, such as IDH1 and MAP2." (PMID 24858213, 2014).
autism (5 papers, 2015 to 2022). Persistent deficits in social interaction and communication and interaction as well as a markedly restricted repertoire of activity and interest as well as repetitive patterns of behavior. "In addition, the MAP2 gene has been identified a good candidate for the generation of a preserved speech variant (PSV) in a patient with autism and Rett-like features." (PMID 26061495, 2015). "Though inconclusive, these data raise the possibility that MAP2 levels are reduced in at least some cases of autism." (PMID 36187353, 2022). "Moreover, case study reports of rare 2q34 deletions—which encompass the MAP2 gene—have described autism-like outcomes." (PMID 36187353, 2022). "This may warrant further investigation of MAP2 abundance and function in autism." (PMID 36187353, 2022). "In several case reports of intellectual disability and autism, reduced numbers of MAP2-IR+ neurons and dendrites has been noted, without a change in total neuron number." (PMID 36187353, 2022). "Importantly, in the context of the hyperglutamatergic theory of autism, MAP2 phosphorylation is also regulated by synaptic activity (glutamate acting through NMDA receptor induces rapid dephosphorylation of MAP2 at (Ser136))." (PMID 36551785, 2022). "The higher levels of MAP-2, NFP, MBP, MAG, α-synuclein S100B and GFAP (3.2 to 4.8-fold) autoantibodies reported in ASD children warrant further research for developing autoantibodies screening as a biomarker for detection of early autism." (PMID 31035713, 2019). "Additionally, in postmortem brain tissue from individuals with autism, dendritic spine morphology shifts towards more immature phenotypes (Martínez-Cerdeño, 2017), which could result from a lack of MAP2-mediated activity-dependent spine growth." (PMID 36187353, 2022).
dementia (5 papers, 2009 to 2025). Loss of intellectual abilities interfering with an individual's social and occupational functions. "Dementia is also a primary symptom in MPS IIIB and, remarkably, when Naglu−/− mice were stained for MAP2, the results showed that MAP2 was reduced when compared to wild type." (PMID 37189853, 2023). "This decrease in cholesterol availability is linked to reduced nuclear localisation and activity of ERRα, as evidenced by the lower number of MAP2+ nuclear ERRα+ neurons in the brains of females with and without dementia than in the brains of their male counterparts." (PMID 41274899, 2025). "In comparison with the control group and the dementia groups without LBs, the LBV group had significantly lower levels of syntaxin and SNAP-25 (23%) in the neocortex, and depletion of MAP2 (64%), SNAP-25 (34%), and α-synuclein (44%) proteins in the medial temporal lobes." (PMID 20024519, 2009).
diabetes (5 papers, 2014 to 2019). "Furthermore, total membranes from the hippocampus of GK and control rats also displayed similar MAP2 immunoreactivity (caffeine P = 0.129, diabetes P = 0.154, interaction P = 0.915)." (PMID 30686981, 2018). "Interestingly, in the diabetic mouse model of diabetes induced with streptozotocin, an increase in fetal neurogenesis in terms of MAP2 expression in the telencephalon is reported at E11.5." (PMID 29311766, 2017). "Consistent with previous studies, the present study confirmed that diabetes induces the accumulation of Aβ1-42 in hippocampal CA1 and CA3 and reduces the expression of BDNF and MAP2." (PMID 31788335, 2019). "In the absence of diabetes, AD parietal cortices had decreased mtDNA, reduced MAP2 (neuronal) and increased GFAP (astrocyte) mRNA, relative to NCI." (PMID 31388037, 2019).
oral cancer (5 papers, 2012 to 2025). "A possible oncogenic role for microtubule-associated protein 2A (MAP2A) was suggested in oral cancer." (PMID 23028842, 2012). "MAP2 has been observed with cell migration and invasion in epithelial and oral cancer cells." (PMID 34068980, 2021). "MAP2 over-expression has been shown in malignant diseases such as cutaneous melanoma, pulmonary carcinoid tumor and small cell carcinoma and it has been correlated with cell motility and invasion in epithelial and oral cancer cells." (PMID 34068980, 2021). "MAP2 expression is correlated with cell motility and invasion in epithelial and oral cancer cells." (PMID 30696040, 2019). "MAP2 has been reported to be involved with malignant oral cancer tissues by playing important roles in neuronal and non-neuronal development." (PMID 25707620, 2015).
brain infarct (4 papers, 2016 to 2022). "In the same set of brains, the brain infarction expanded from the striatum at 6 h after tFCI into the cortex within 24 h, as indicated by loss of the neuronal marker microtubule-associated protein 2 (MAP2)." (PMID 26813496, 2016). "Accordingly, this training mechanism was experimentally validated to outperform a conventional treadmill, particularly with respect to the brain infarct volume, the lesion volume, the number of MAP2 positive cells and the level of cortisol." (PMID 31603928, 2019). "We further examined NeuN- and MAP2-stained neurons to assess the brain infarct damage." (PMID 29544517, 2018). "Cerebral infarction was assessed by TTC staining at day 2 after surgery and MAP2 staining at day 21 after surgery." (PMID 36177058, 2022). "To explore the effects of different surgical approaches on brain infarcts, we used TTC staining 2 days after surgery for infarct volume calculation and MAP2 immunofluorescence staining 21 days after surgery for tissue loss assessment." (PMID 36177058, 2022).
Down syndrome (4 papers, 2012 to 2023). "In 1997 evidence was already present that MAP2 expression is reduced in patients with Rett syndrome while being upregulated in Down syndrome." (PMID 29632546, 2018). "A link between increased MAP2 expression and dendritic pathology in Down’s syndrome has also been established." (PMID 29509660, 2018).
metastatic melanoma (4 papers, 2010 to 2022). A melanoma that has spread from its primary site to another anatomic site. "In in vitro studies forced expression of MAP2 via epigenetic modification in metastatic melanoma cells, has been found to induce mitotic spindle defects, apoptosis and inhibition of cell growth." (PMID 29179510, 2017). "Similarly, HDACi have been shown to promote MAP2 expression and induce benign neuron-like differentiation in a metastatic melanoma mouse cell line in vitro." (PMID 29794999, 2018).